HDAC6 (histone deacetylase 6)
Diseases named in the same sentence as HDAC6 in open-access papers (continued):
Sharing a sentence is not in itself a finding about the gene and the disease.
cancer (continued). "Therefore, the aim of this study is to screen for potential repurposable FDA-approved drugs against HDAC6 (braking the cancer progression) and VISTA (removing the imposed immunosuppression) as a novel dual therapeutic strategy for cancer treatment." (PMID 37660065, 2023). "The highly selective HDAC6 inhibitor TA has been evaluated in the therapeutic areas of neurodegenerative diseases, cancer, and COPD with no apparent adverse effects." (PMID 37545520, 2023). "Since HDAC6 is not a valid target to stall cancer cell proliferation, the predominant inhibition of class I HDACs by KH16 appears most important for its anti-cancer effects." (PMID 37509312, 2023). "Histone deacetylase 6 (HDAC6), a major deacetylase enzyme, is a promising target for cancer therapy; however, the molecular mechanism regulating cancer pathogenesis is largely unknown." (PMID 36639650, 2023). "As evidence highlighted that simultaneous inhibition of HDAC6 and HDAC8 could lead to synergistic therapeutic effects in cancer and could be beneficial in different pathologic conditions, several dual HDAC6/8 inhibitors have been recently disclosed." (PMID 36077415, 2022). "Its cellular localization and non-epigenetic roles in cancer progression provide a rationale for therapeutic use of selective HDAC6 inhibitors in preclinical metastasis models." (PMID 36559094, 2022). "Among the HDAC inhibitors we tested, Belinostat, Romidepsin (HDAC1 and 2), and Tubastatin (HDAC6) inhibited acetylation at H3 and H4 using cancer cells but did not affect the ability of Mtb-infected MФs to present antigen to CD4 T cells." (PMID 35590096, 2022). "HDAC6 is required for activation of MAPK and PI3K signaling cascades, which may contribute to anchorage-independent growth of cancer cells." (PMID 36505774, 2022). "HDAC6, a member of class IIb HDAC, has been disclosed as an interesting target for cancer therapy." (PMID 35163593, 2022). "Moreover, as a special HDAC6 inhibitor, Tubastatin A (TST) can affect cell growth and promote structural modifications in cancer cells and parasites, which are potential anti-Toxoplasma gondii chemotherapeutics." (PMID 36451815, 2022). "Furthermore, TH34, an HDAC6/8/10 inhibitor, and droxinostat, an HDAC3/6/8 inhibitor, have demonstrated anti-cancer effects in several cancer types." (PMID 35955780, 2022). "Histone deacetylase 6 (HDAC6) is a therapeutic target in non-central nervous system (CNS) cancers that is receiving increasing scrutiny in GBM." (PMID 33915983, 2021). "In contrast to most HDACs, HDAC6 is a cytoplasmic non-histone deacetylase enzyme that deacetylates cancer relevant cytoplasmic substrates such as α-tubulin and Hsp90." (PMID 34959719, 2021). "The Cancer Genome Atlas (TCGA), Genotype-Tissue Expression (GTEx), and Cancer Cell Line Encyclopedia (CCLE) datasets were used to determine the expression levels, prognosis, tumor progression, immune checkpoints, and immune metabolism of HDAC6 in 33 tumors." (PMID 34485153, 2021). "Of particlar interest, genome-wide DNA methylation screening detected 15 histone-related genes, including histone deacetylase 6 (HDAC6), to be hypermethylated, which is in congruent with the observed decreased HDAC activity in valeric acid treated cancer cells." (PMID 33510252, 2021). "Of note, HDAC6 seems to have cancer-specific functions as Hdac6-knock-out mice showed no obvious phenotype under non-inflammatory conditions." (PMID 35008680, 2021). "The HDAC6-specific inhibitor ACY241 decreases the number of Treg cells (CD4+CD25+FoxP3+), but increases the number of activated CD8+ T cells by activating AKT signaling to induce anti-cancer effects against multiple myeloma." (PMID 32626712, 2020). "Additionally, HDAC6 was responsible for Wnt‐ and EGF‐induced nuclear localization of β‐catenin through deacetylating β‐catenin at different lysine sites in cancer cells." (PMID 32985730, 2020).
cancer (continued). "GRK5 and HDAC6 form a signaling complex where GRK5 phosphorylates HDAC6 at Ser-21, promoting deacetylase activity, which may contribute to PTX resistance in cancer cells." (PMID 33182737, 2020). "Furthermore, HDAC6 and HDAC8 was found to regulate cancer cell migration and invasion via α-tubulin acetylation." (PMID 33024443, 2020). "Some depsipeptides display a greater affinity for HDAC1 than HDAC6 and class II HDACs, but this does not appear to limit their activity as anti-cancer agents judging by in vitro effects in cancer cells." (PMID 33312959, 2020). "Both HDAC3 and HDAC6 could increase the expression of survivin and siRNA treatment of HDAC3 and HDAC6 showed a similar effect of SAHA and induced autophagy in MCF7 and MDA-MB-231 cancer cells." (PMID 33193750, 2020). "HDAC6 is known to be overexpressed in many cancer types and the complete genetic abrogation of HDAC6 does not impair normal cellular functions." (PMID 30992475, 2019). "Therefore, HDAC6 can be a cancer-specific target of malignant phenotypes mediated by STIM1-dependent SOCE, at least for cancers with upregulation of HDAC6 and STIM1." (PMID 31252656, 2019). "Thus Aspirin modulates the Wnt/β-catenin pathway, with HDAC6 as a direct target protein, and FMOD as a downstream transcriptional target gene in cancer metastasis, which reveals a significant link between regulation of FMOD with Aspirin action." (PMID 31824307, 2019). "In addition to this mechanism, which is transversal to different types of cancers, we also showed that cancer cells characterized by peculiarly high RUNX2 levels (TPC1) rely on the additional activity of HDAC6." (PMID 31395086, 2019). "In keeping with these findings, we further found that ectopic expression of SPOP WT, but not cancer-derived mutants, could promote the degradation of HDAC6 in cells in a dose-dependent manner, which largely was due to deficiency in promoting the poly-ubiquitination of HDAC6 in cells." (PMID 28599312, 2017). "Due to the similarities between cancer and PAH, we hypothesized that HDAC6 expression is increased in PAH-PASMCs to face stress allowing them to survive and proliferate, thus contributing to vascular remodeling in PAH." (PMID 28674407, 2017). "HDAC6 inhibitors demonstrated strong antiproliferative activity, induced cell death in several cancer cell lines, and reduced tumor mass without overt toxicity." (PMID 28203307, 2017). "Both HDAC5 and HDAC6 could influence the metastasis of A375 cells by regulating MMP9 and vimentin, both markers for the metastasis ability of cancer cells." (PMID 26747087, 2016). "Previous studies identified that HDAC6 displayed as a better target than other HDACs because of its high relevant cancer-related non-histone substrates without the severe toxicity." (PMID 25946558, 2015). "Of those differentially expressed in our study, 14q32 miRNAs having confirmed targets include miR-127 (located within a CpG island and silenced in many cancers) targeting BCL-6, miR-154 targeting CCND2, miR-433 targeting HDAC6, miR-485-3p targeting NF-YB and miR-539 targeting HLCS." (PMID 23717541, 2013). "It seems that HDAC6, protein kinase C alpha (PKCα), and beta-catenin are all involved in the induction of type I interferon (IFN) transcription that occurs when the cell becomes infected with a cancer virus." (PMID 23644884, 2013). "Moreover, CYLD is also able to inhibit HDAC6, a member of the HDAC family whose major substrate is α-tubulin, has become a target for drug development to treat cancer due to its major contribution in oncogenic cell transformation." (PMID 22911729, 2012). "Although HDAC6 overexpression was found in certain types of cancer, the role of HDAC6 in tumorigenesis has not been established until the report by Dr. T-P Yao’s group." (PMID 22957056, 2012). "Therefore, many of the earlier studies of HDAC6 inhibition in cancer did not specify its specific mode of action." (PMID 39941046, 2025).
cancer (continued). "Interestingly, an increasing number of studies, including preclinical models, have reported the immunoregulatory effect of HDAC6 inhibitors on cancer suppression and prolonged survival with no significant toxicity." (PMID 39800760, 2025). "The HDAC6 inhibitor tubacin has been shown to promote cell death through the intrinsic apoptotic pathway by inducing the expression of cellular stress genes such as DDIT4 (RTP801/Dig2/REDD1) and DDIT3 (CHOP/GADD153), thereby triggering DNA damage in various cancer cells." (PMID 40843669, 2025). "Additionally, the specific HDAC-6 isoform inhibitor Tubacin showed significantly higher toxicity than the non-specific HDAC inhibitors in 3D cancer spheroids." (PMID 41395596, 2025). "The coordinated inhibition of HDAC6, HDAC3, and HDAC4 by BKS-112 may synergistically contribute to its potent anticancer effects, as these isoforms play distinct but complementary roles in cancer cell survival and progression." (PMID 41300448, 2025). "Notably, HDAC6 inhibition activates DNA damage repair pathways by upregulating cellular stress genes such as DDIT4 (RTP801/Dig2/REDD1) and DDIT3 (CHOP/GADD153), highlighting its potential as a therapeutic target in cancer treatment." (PMID 40843669, 2025). "Unlike its counterparts, HDAC6 targets cytoplasmic proteins for acetylation, thereby regulating numerous biological processes pivotal for cancer initiation, promotion, proliferation, metastasis, and the maintenance of cancer stem cells." (PMID 39063958, 2024). "Additionally, HDAC6 and DNMT3B are emerging as important therapeutic targets for cancer." (PMID 39411320, 2024). "Among these, the upregulated gene, the HDAC6, a member of the HDAC family, is involved in cell survival, cell movement, cell cycle progression, protein degradation, and developmental events and has become a promising target for managing various human diseases, including cancer." (PMID 39411320, 2024). "Our study suggests that both HDAC1 and HDAC6 were inhibited by TSC to a similar extent as trichostatin A. Since class I HDAC has a pivotal role in cell survival and proliferation, it is believed that hyperactivation of HDAC1 is positively correlated with cancer development." (PMID 38675387, 2024). "Considering that HDAC6 is involved in multiple cancer-related pathways and that there was no severe toxicity with HDAC6 inhibition in animal models, some therapeutic advantages have been postulated for selective therapeutic targeting of HDAC6." (PMID 38258065, 2023). "Moreover, selective HDAC6 inhibition was reported to downregulate the expression of TGF-βRI and the phosphorylation of Smad3 and EMT-inducing transcription factor Snail that led to the preserved expression of E-cadherin in cultured cancer cells." (PMID 38258065, 2023). "Interestingly, ACY-1215, when used at HDAC6 selective concentrations (up to 2 μM), did not promote apoptosis; however, if used in combination with other anti-cancer drugs, it proved to be more effective." (PMID 35159049, 2022). "Some HDACs may hold the effects on both oncogene and tumor suppressor in cancers (e.g. HDAC6 is involved in tumor suppression by non-epigenetic regulation in HCC)." (PMID 36185276, 2022). "As our results suggest, dual inhibitors targeting both HDAC6 and HDAC8 may prove to be an effective anti-cancer agent as they would decrease the undesirable cytotoxic side effects from having to use multiple inhibitors while still providing the anti-cancer benefits of inhibiting HDAC6 and HDAC8." (PMID 35955780, 2022). "HDAC6, which is overexpressed in clinical GBM tumors, TMZ-resistant GBM cells and GBM stem-like tumorspheres, affects the expression of cell-cycle-related genes and cancer stemness-related genes through regulating acetylation levels of Sp1 transcription factor." (PMID 34584069, 2021). "In particular, HDAC6 appears to have both positive and negative effects in different cancers." (PMID 34365463, 2021).
cancer (continued). "Last but not least, HDAC6 has been widely reported in cancer therapy." (PMID 34530730, 2021). "However, we found that citarinostat had a significantly reduced effect on HDAC6 in ABCB1-overexpressing KB-V-1 and ABCG2-overexpressing S1-M1-80 cancer cells as compared to the respective parental KB-3-1 and S1 cancer cells." (PMID 33807514, 2021). "In contrast to other HDACs, HDAC6 regulates the acetylation of non-histone proteins such as α-tubulin, β-catenin, cortactin, and heat shock protein 90 and participates in cancer development and progression." (PMID 30594243, 2018). "The targeted inhibition of HDAC6 also elevates acetylation of HSP90, which decreases the binding between HSP90 and ATP, thus reducing the combination of chaperone and oncogene, which could be of great importance in cancer treatment." (PMID 30176876, 2018). "We therefore hypothesized that, as observed in many cancers, HDAC6 is overexpressed in PAH contributing to proliferation and resistance to apoptosis of PASMCs and that selective HDAC6 inhibition may represent a promising novel approach for the treatment of PAH." (PMID 28674407, 2017). "However, depletion of Cullin 3, but not Cullin 1, elevated the protein abundance of endogenous HDAC6 in multiple cancer cell lines including HT29, HCT116, PC3, and HeLa." (PMID 28599312, 2017). "Notably, compared to SPOP WT, cancer-derived SPOP mutants failed to decrease the protein abundance of endogenous HDAC6 in cells." (PMID 28599312, 2017). "Thus, we have characterized novel compounds 9a-d as HDAC6 selective inhibitors in vitro and shown that three of them (9b, 9c and 9d) have specific antiproliferative activity against cancer but not normal cells." (PMID 26698121, 2015). "Not all pro-cancer interactions of HDAC6 involve deacetylation." (PMID 23644884, 2013). "Furthermore, what makes a cancer cell sensitive to HDAC6 inhibition has not been clearly defined." (PMID 39941046, 2025). "We hypothesize that HDAC6 could be a part of CoREST and other transcriptional repressor complexes in other cancers as well where inhibiting both LSD1 and HDAC6 can lead to comprehensive inhibition of the transcription complex leading to synergistic anti-cancer activity." (PMID 36595522, 2023). "In addition to the inactivation of Class I HDAC activity, panobinostat strongly inhibited HDAC6 activity (and also, therefore, with high probability, its profibrotic signalling) in IPF fibroblasts, which is in accordance with studies of its marvellous efficacy in various cancers." (PMID 35626663, 2022). "However, a key impact of HDAC6 on an important developmental regulator like β-catenin is hard to reconcile with the lack of phenotypic abnormalities in HDAC6 knockout mice and with accumulating evidence that an inhibition of HDAC6 does not affect cancer cell growth." (PMID 31561534, 2019). "Overexpression of TDP-43 and HDAC6 in the late stage GBM patients raised the possibility that expression levels of TDP-43 and HDAC6 could be induced by cellular stress triggered by therapeutic treatment or nutrient deprivation that is common to highly malignant and advanced cancer cells." (PMID 28915616, 2017). "Importantly, cancer-derived SPOP mutations disrupted the binding between SPOP and HDAC6 and failed to promote HDAC6 poly-ubiquitination and subsequently degradation, which might lead to elevated levels of HDAC6 to promote tumorigenesis." (PMID 28599312, 2017). "Colvin underlined that although potential emerging drugs, including histone deacetylase 6 (HDAC6) inhibitors, are now in early-phase clinical studies for cancer therapy, no preventative treatments have demonstrated meaningful clinical benefit." (PMID 37623452, 2023). "In line with these ideas, we identified that HDAC6 inhibitors sensitize non-mesenchymal TNBC cells and some luminal cancer cells to cysteine deprivation." (PMID 34040090, 2021).
cancer (continued). "Class II HDACs, including HDAC5, HDAC6, and HDAC9, have been reported to catalyze the deacetylation of cytoplasmic, non-histone proteins in cancer cells." (PMID 32977608, 2020). "Notably, although bafilomycin A1 treatment could dramatically elevated the protein abundance of LC3B-II, a biomarker of autophagy, it did not lead to significant changes of HDAC6 protein level in various cancer cell lines including HCT116, DLD1, and HeLa cells." (PMID 28599312, 2017). "These inhibitors appear to primarily affect non-histone targets of HDAC6 including α-tubulin and HSP90 and have beneficial effects in disease models including cancer but also extending to neurodegeneration and immunity." (PMID 26698121, 2015). "Interestingly, tubastatin A, a selective HDAC6 inhibitor, overcomes both ferroptosis resistance and radioresistance in cancer cells by inhibiting GPX4 enzymatic activity, independent of histone deacetylase 6 (HDAC6) inhibition." (PMID 39534872, 2024). "Among the cytosolic deacetylases responsible for the deacetylation of nonhistone proteins (i.e., HDAC6, SIRT1, and SIRT2), the expression of SIRT1/2 was considerably higher in cancer cells (i.e., A549 and HCC1806 cells) than in normal tissue cells (i.e., BEAS-2B and HMLE cells)." (PMID 38649663, 2024). "Currently, there are no FDA-approved HDAC6 inhibitors; however, the selective HDAC6 inhibitor ACY-1215 has shown potential in numerous phase I and II clinical trials with current investigation into use in combinatorial cancer treatment." (PMID 39790566, 2024). "Notably, cancer-derived SPOP mutants disrupted their binding with HDAC6 and thereby failed to promote HDAC6 degradation." (PMID 28599312, 2017). "Interestingly, targeting HDAC3 and HDAC6, but not other HDAC isoforms, by siRNA/pharmacological inhibitors mimicked the effects of SAHA in modulating the acetylation, expression, and nuclear translocation of survivin and induced autophagy in MCF7 and MDA-MB-231 cancer cells." (PMID 27065869, 2016).